RHOG (ras homolog family member G)
Description:
Plays a role in immunological synaptic F-actin density and architecture organization. Regulates actin reorganization in lymphocytes, possibly through the modulation of Rac1 activity. Acts as an activator of the ELMO-DOCK-Rac pathway. Required for the formation of membrane ruffles during macropinocytosis. Plays a role in cell migration and is required for the formation of cup-like structures during trans-endothelial migration of leukocytes. Binds phospholipids in an activation-dependent manner; thereby acting as an anchor for other proteins to the plasma membrane (PM). Plays a role in exocytosis of cytotoxic granules (CG) by lymphocytes/Component of the exocytosis machinery in natural killer (NK) and CD8+ T cells. Promotes the docking of cytotoxic granules (CG) to the plasma membrane through the interaction with UNC13D. Involved in the cytotoxic activity of lymphocytes/primary CD8+ T cells. (Microbial infection) In case of Salmonella enterica infection, activated by SopB and ARHGEF26/SGEF, which induces cytoskeleton rearrangements and promotes bacterial entry.
Synonyms: ARHG; MGC125835; MGC125836
Tractability: Small molecule: a structure with a bound ligand is known. Antibody: UniProt places it where antibodies can reach, with high confidence; its Gene Ontology location is reachable by antibodies, with high confidence. PROTAC: ubiquitination databases record sites on it; its protein half-life has been measured.
Gene: Protein-coding gene on chromosome 11 (3,826,978 to 3,840,985, reverse strand). Ensembl gene ENSG00000177105.
Subcellular location: Cell membrane
Pathways (Reactome):
Signal Transduction: PI5P, PP2A and IER3 Regulate PI3K/AKT Signaling; PIP3 activates AKT signaling; RHO GTPases activate KTN1; RHOG GTPase cycle
Disease: Constitutive Signaling by Aberrant PI3K in Cancer
Hemostasis: GPVI-mediated activation cascade
Immune System: Neutrophil degranulation
Gene Ontology:
Molecular function: GTPase activity; protein binding; G protein activity; GTP binding
Biological process: actin cytoskeleton organization; activation of GTPase activity; cell chemotaxis; positive regulation of DNA-templated transcription; positive regulation of protein localization to plasma membrane; Rac protein signal transduction; regulation of postsynapse assembly; Rho protein signal transduction; actin filament organization; establishment or maintenance of cell polarity; positive regulation of cell population proliferation; regulation of cell shape; small GTPase-mediated signal transduction
Cellular component: extracellular exosome; focal adhesion; glutamatergic synapse; postsynapse; cytoplasmic vesicle; cytoskeleton; cytosol; endoplasmic reticulum membrane; plasma membrane; secretory granule membrane
Genetic constraint (gnomAD): Loss-of-function variants: 1 observed, 12.91 expected, observed/expected ratio (o/e) 0.0774, 90% interval 0.027 to 0.37. The upper end of that interval is the gene's LOEUF score, 0.37, which puts it in group 1 of 6, group 1 being the genes least tolerant of losing a copy. Missense variants: 114 observed, 274.14 expected, observed/expected ratio (o/e) 0.42, 90% interval 0.36 to 0.49. Synonymous variants: 129 observed, 119.2 expected, observed/expected ratio (o/e) 1.08, 90% interval 0.94 to 1.25.
Homologues: Orthologues: chimpanzee RHOG (100% identical), mouse Rhog (100% identical), rat Rhog (100% identical), dog RHOG (99% identical), guinea pig RHOG (99% identical), macaque RHOG (99% identical), rabbit RHOG (99% identical), pig RHOG (99% identical), tropical clawed frog rhog (83% identical), zebrafish rhogb (80% identical), zebrafish rhoga (73% identical), Caenorhabditis elegans mig-2 (60% identical). Paralogues in human: RAC2 (71% identical), RAC1 (71% identical), RAC3 (70% identical), CDC42 (61% identical), RHOQ (57% identical), RHOA (54% identical), RHOB (54% identical), RHOC (54% identical), RHOJ (53% identical), RHOU (50% identical), RHOF (47% identical), RHOV (47% identical), and 10 more.